IL10 (interleukin 10)
Diseases named in the same sentence as IL10 in open-access papers (continued):
Sharing a sentence is not in itself a finding about the gene and the disease.
infection (continued). "Interestingly, although the levels of the IL-10 increased significantly (p<0.05) in the spleen the levels were only minimally increased in the draining lymph node at the site of infection as reflected by antigen specific recall stimulation of cells from the MLN." (PMID 28650985, 2017). "Besides, high levels of IL-10 could induce a state of functional immunoparalysis, leading to an incontrollable infection." (PMID 28628675, 2017). "Studies carried out on mice observed that overexpression of IL-10 may not be important for susceptibility to initial infection with M. tb but may play a role in reactivation of the latent disease." (PMID 28951522, 2017). "Furthermore, the expressions of TGF-β and IL-10 in the cystic wall obviously decreased after irradiation, indicating that irradiation contributes to the attenuation of the inflammatory reaction and infection in the host." (PMID 28464914, 2017). "The active production of IL-10 by infected phagocytic cells probably aids the intracellular survival of the bacteria and its dissemination from the intestine in early stages of the infection, favoring the colonization of other tissues, such as spleen and liver." (PMID 28824622, 2017). "Therefore, circumventing the inhibitory effect of IL-10 in the early stage of PRRVS vaccination/infection could be a challenge for PRRSV vaccine development." (PMID 28839507, 2017). "Strikingly, the IL-10 induction was influenced by both the bacterial strain and a person-strain interaction, which might play an important role in reducing the severity of symptoms after infection and the time of shedding after resolution of symptoms." (PMID 28196097, 2017). "Furthermore, the infection of activated cells induced production of cytokines known as deactivating factors for macrophage like TGF-β and IL-10, that when associated with decreased expression of MHC II and CD80 represent a powerful mechanism to modulate parasite growth in this cell line." (PMID 28620374, 2017). "For example, animals that are genetically deficient in IL-10 or are treated with antibodies that neutralize IL-10 die rapidly when infected with pathogens due to the overproduction of proinflammatory cytokines rather than a lack of control of infection." (PMID 28138552, 2017). "Indeed, we also confirmed that upon FMDV O1 Manisa and A24 Cruzeiro infection, we could detect IL-10 in cattle sera, which peaked at day 4 following infection with strain A24, but was variable in four steers infected with O1Manisa." (PMID 27008425, 2016). "Additionally, it should be noted that even during the early onset of infection with negative DTH response (III profile) IL-6 showed significantly higher serum levels than those of TNF-α, IL-4, and IL-10, suggesting that it exerts a latent immunopathogenic effect even during early infection onset." (PMID 27051668, 2016). "Additionally, the production of IL-10 was increased in IL-22−/− mice upon infection." (PMID 27650379, 2016). "However, it is so far unclear whether the induction of IL-10 or IL-6 could directly increase cellular viral replication or whether they are only the byproducts of DENV-ADE infection." (PMID 26923481, 2016). "Strikingly, expression of regulatory factors (IL-10, IL-25, Foxp3), which arise following H. diminuta infection, were either enhanced or sustained in IL-22-/- mice, uncovering a novel role for IL-22 as a brake for these regulatory events following infection with this parasitic helminth." (PMID 27055194, 2016). "Thus, we hypothesize that infection stimulates regulatory/suppressor T-cells that can favor bacterial persistence through the secretion of IL-10." (PMID 28018318, 2016). "Using IL-10 reporter mice, we observed that at day 9 after LCMV-Cl13 infection, IL-10 expressing cells were distributed throughout the red pulp and marginal zone of the spleen consistent with DC and macrophage localization of IL-10 at this time point during infection." (PMID 26808628, 2016).
infection (continued). "IL-10 may control IFN-γ synthesis during infection, thereby avoiding Th1 over-reactivity." (PMID 27608632, 2016). "With respect to in vitro interleukin-10 (IL-10) production, a significant statistical difference was observed in So-stimulated cells at 60 days post-inoculation (p < 0,05) in comparison to the previous infection times, and also in comparison to cells stimulated with Se at this same time point." (PMID 27608632, 2016). "In these studies, mice which generated complete sterilizing immunity during primary infection due to deficiency in Treg IL-10 production were not protected against secondary challenge, implicating a role for host-pathogen co-evolution to promote mutual survival." (PMID 27806117, 2016). "Moreover, studies performed on patients infected with HIV revealed that, during infection, PD-1 is up-regulated on monocytes and the interaction of PD-1 with PD-L1, expressed on other cell types, induced IL-10 production, which in turn led to CD4+ T cell dysfunction." (PMID 26700461, 2016). "However, in the Ft infection model we observed no decrease in Th2 cytokines such as IL-4 or IL-10 in Nlrp3-deficient mice at any time following infection, but IFNγ production was slightly elevated at 6 days post-infection." (PMID 27926940, 2016). "The decrease in frequency and numbers of cNK cells in spleen after infection with replicating parasites may also be affected by IL-10 production, since IL-10 is an immunoregulatory cytokine that balances the proinflammatory immune responses that can be detrimental to the host." (PMID 27721814, 2016). "Furthermore, the infection phase may also influence the impact of IL-27 on IL-10+ T cell development." (PMID 27926930, 2016). "However, since TNF-α and IL-10 are major pro- and anti-inflammatory cytokines found to be involved in a variety of infections in animal and cell culture models, it is feasible that it plays a general role widely, rather than specifically toward select pathogens." (PMID 27761434, 2016). "Of those, only TNF-α and IL-10 had negative associations with infection status." (PMID 27418744, 2016). "Thus, given our study design, we expect that our results on the association of TNF-α/IL10 cytokine ratio are predictive of later infections, rather than a consequence of pathogenic encounter." (PMID 27761434, 2016). "However, because some cytokines such as IL-1β, IL-6, or IL-10 typically produced during infection are known to alter DC differentiation, indirect mechanisms might be of similar importance." (PMID 26870700, 2016). "Thus, IL-27 production in response to MCMV is dependent upon type-1 IFNR signaling, and this axis acts during the initial days of infection to promote the accumulation of MCMV-specific IL-10+CD4+ T cells, subsequently promoting virus persistence and shedding from the mucosa." (PMID 27926930, 2016). "Although the YopM effect on macrophage gene expression after 6 h of infection may be due to complex autocrine mechanisms and feed back loops, immunosuppressive mediators like IL-10 whose expression was upregulated after 1.5 h of infection already could drive this response." (PMID 27300509, 2016). "However it is currently unknown how the expansion of these cells is controlled during infection, and whether IL-10 production by T cells impacts on MCMV chronicity." (PMID 27926930, 2016). "Stimulation of TLR by bacterial recognition activated cytokine cascades such as IL-6 and IL-10 signaling pathways predominantly at 1 and 2 dpi, which lead to recruitment of other immune cells (e.g., neutrophils, dendritic cells) to the infection site in order to clear infection." (PMID 26738723, 2016). "Thus, prominent blood brain barrier damage and permeability present in experimental WNV- or LCMV-infection explains the restoration of antiviral immunity in the CNS and beneficial effects of anti-IL-10/IL10-R treatment in these infection models in contrast to TME." (PMID 27611574, 2016).
infection (continued). "Our study showed that mice infected with H. pylori PMSS1 strain have increased levels of circulating IL-10, an important mediator of Treg cell function and increased Treg cell transcription factor FoxP3 mRNA expression in their stomachs after four weeks of infection." (PMID 25807464, 2015). "This suggests that during natural infection, where repeated exposures to infective cercariae are likely to be common for residents of schistosome-endemic areas, IL-10 could play an important role in limiting leukocyte mediated tissue damage associated with migration of larvae through the skin." (PMID 25974019, 2015). "However the situation in live infection is much more complex, characterized by mixed Th1/Th2 immune response, with the activation of regulatory mechanisms reflected in the highly increased production of IL-10 and TGF-β." (PMID 26114122, 2015). "To investigate how IL-33 might interfer with the host immune response, we measured the levels of the key Th1 cytokines (IFN-γ, IL-12 and TNF-α), key Th2 cytokines (IL-4, IL-5 and IL-13), and the regulatory cytokine IL-10 in the serum at various time-points after infection with PbA." (PMID 25659095, 2015). "Furthermore, secretion of IL-10 by Treg cells at the site of infection may suggest the existence of suppressive mechanisms influencing the ability of effector T cells to promote pathogen eradication." (PMID 26512987, 2015). "Similarly, previous results from our laboratory have shown that MCP-1α, MIP-1α, RANTES, IFN-γ, and IL-8 were increased upon RSV-infection in neonatal lambs on day 6, whereas the anti-inflammatory mediator, IL-10, was down regulated at day 6 post-infection, but increased on day 3 post-infection." (PMID 26641081, 2015). "In addition, IL-10 is a regulatory cytokine believed to play a key role in suppressing inflammatory and immunopathological responses and hence contributing to the outcome of infection." (PMID 25897840, 2015). "Thus, we demonstrate that a number of CD4+ T cells with specificity to commensal antigens are present in naïve skin and we conclude that infection with schistosome cercariae enhances the exposure of CD4+ T cells to SC antigen resulting in the observed IL-10 production." (PMID 25974019, 2015). "However, here we demonstrate that production of IL-10 by dermal CD4+ T cells occurs very early during the initial stages of S. mansoni infection, well in advance of egg deposition, which is a hallmark of chronic/long term infection." (PMID 25974019, 2015). "In the current study we hypothesized that F. tularensis polarizes antigen presenting cells (APCs) during the first 48 hours post-infection towards an anti-inflammatory status, characterized by IL-10 production, thus allowing the pathogen to avoid protective anti-bacterial innate immune responses." (PMID 26114641, 2015). "Importantly, the decrease of IL-10 in the mAb-iFt immunized mice observed at 96 hours post-infection was consistent with our previous observation, indicating that FcγR targeting shifts towards a pro-inflammatory cytokine profile at the early stages of F. tularensis infection." (PMID 26114641, 2015). "In the current study, we hypothesized that F. tularensis polarizes antigen presenting cells during the early stages of infection towards an anti-inflammatory status characterized by increased synthesis of IL-10 and decreased production of IL-12p70 and TNF-α in an IFN-ɣ-dependent fashion." (PMID 26114641, 2015). "This early and rapid release of IL-10 has the potential to greatly modulate the immune response in the skin by limiting inflammation and tissue damage, plus conditioning the microenvironment recruited immune cells will encounter as they infiltrate the infection site." (PMID 26116503, 2015).
infection (continued). "Thus, the infected mice that did not receive IL-10 treatment exhibited a significantly more severe clinical response compared with the IL-10 treated animals after day 29 of infection, while the maximum mean clinical score in the IL-10 treated mice was less than 1.6." (PMID 26505761, 2015). "In addition to IL-27, type I interferon affects IL-10 production during infection." (PMID 25651926, 2015). "Thus, different infections elicit different CD4+ T cells producing IL-10." (PMID 26417443, 2015). "Moreover, Trichuris infection was associated with increased plasma levels of pro-inflammatory (IL-1β and IL-17α), anti-helminthic (IL-13) and regulatory (IL-10) cytokines, which closely correlated with each other; showing a mixed cytokine response to infection with Trichuris." (PMID 24675895, 2014). "Notably, a high viral load of DENV infection alone, as demonstrated by plaque assays (P<0.001), significantly (P<0.001) induced IL-10 production in a multiplicity of infection (MOI)-dependent manner, although phosphorylation of PKB at Ser473 and GSK-3β at Ser9 was not increased." (PMID 25412261, 2014). "IL-10 is a powerful T helper 2 regulatory cytokine and plays an essential role during the latent TB stage, where increased production of this cytokine promotes reactivation of disease in mice and suppression of cell-mediated immunity against the intracellular infection." (PMID 24523896, 2014). "Infected burn mice had a systemic anti-inflammatory response following infection, which was marked by elevated serum IL-10 levels; therefore, we hypothesized the innate cells were polarized towards an anti-inflammatory phenotype (IL-10+ IL-12−) following burn and infection." (PMID 24454904, 2014). "In contrast to the clear association of IL-10 responsiveness with resistance, IL-17 expression did not correlate with any infection outcome in this study, suggesting that in primary infection at least, this compartment of the immune system is not a critical factor." (PMID 24492801, 2014). "Therefore, we intended to investigate whether IL-10 played a similar role in the regulation of CCR5 expression in macrophages during H37Rv infection." (PMID 24695099, 2014). "In contrast, IL-10 expression is significantly higher in B2 birds at 12 dpi, suggesting that it is much better able to regulate its inflammatory response and that dysregulation of this in A1 birds leads to infection-mediated pathology in the lower intestinal tract." (PMID 24987092, 2014). "Thus, IL-10 can suppress host immune responses during infection by multiple mechanisms." (PMID 25352846, 2014). "After 24 hours of induction, some gene have slightly change, such as CD163 elevated by ST169 (H1N1) (2.37), and IL-10 elevated by HKG9 (H9N2) (2.63), whereas, most of the M1/M2 markers return to the normal level, it seems that influenza virus caused AM immunosuppression after 24 hours infection." (PMID 25105760, 2014). "Thus, simultaneous production of high IL-4 and IL-10 may be the mechanistic determinant of the exacerbated infection observed in the spleen of saponin + LAg immunized mice." (PMID 24428931, 2014). "Similarly, rapid intracellular macrophage growth rates by strains of M. tuberculosis strains correlated with rapid production of IL10 that antagonizes the proinflammatory response by down-regulating the production of TNFα in THP-1 cells during the early stages of infection." (PMID 25111300, 2014). "Therefore, IL-10 appears to play a major role in the course of this chronic infectious disease although the precise mechanisms of action within the site of infection are unknown." (PMID 25210773, 2014). "On the other hand, IL-10 driven inhibition of IFN-γ production suggests that this counter-regulatory mediator may favor a shift toward a Th2 response later in the course of infection, and prevent tissue damage as a consequence of uncontrolled intestinal inflammation." (PMID 23593150, 2013).
infection (continued). "Indeed, the infection with M. leprae suppressed the production of IL-10." (PMID 23782413, 2013). "Similarly, a number of chemokines known to recruit leukocytes to infection sites were upregulated by MØs and DCs during Bb infection, but many of these were suppressed in the presence of Bb-elicited IL-10, particularly the neutrophil-recruiting chemokines such as KC (CXCL1) and MIP-2α (CXCL2)." (PMID 24367705, 2013). "Our findings suggest that a balance of TNF-α and IL-10 defines a granuloma environment that may be beneficial for both host and pathogen, but perturbing the balance could be used as a novel therapeutic strategy to modulate infection outcomes." (PMID 23869227, 2013). "The expression of IL-10, an anti-inflammatory cytokine, was significantly up-regulated in wounds infected with Pseudomonas, while USA300 or mixed-species infection did not cause significant induction of IL-10, although an increasing trend of IL-10 was observed in these wounds." (PMID 23451098, 2013). "The factors that promote T cell IL-10 production are less well defined, but appear to involve strong antigenic stimulation and IL-12 production, both of which may contribute to the IL-10 production that we see in Th1 cells after a high dose infection with L. major." (PMID 23555256, 2013). "Accordingly, IL-10−/− mice develop excessive Th1 cell responses, resulting for example in spontaneous inflammatory bowel disease or overwhelming immunopathology upon infection with parasites like Toxoplasma gondii, Trypanosoma, Schistosoma or Trichinella spiralis." (PMID 23825956, 2013). "A major difference between early and late infection is the evolution of the immune response driven by the continuous release of immunomodulatory/inflammatory factors by the parasite, such as VSG and TSIF, which induce pathogenic TNF-α and IFN-γ while switching off the IL-10 production." (PMID 24204274, 2013). "Another cytokine stimulated by the probiotic treatment was IL-10, which is a typical Th2 cytokine that is initially repressed in virus infected cells but then expressed at higher levels later in infection to control the initial inflammatory response to infection." (PMID 23308134, 2013). "Given that our results showed reduced concentration of IL-10 in the lungs homogenates of 5-LO−/− mice during infection with P. brasiliensis, this may have contributed to the exacerbated production of pro-inflammatory cytokines and chemokines observed in these animals." (PMID 23991239, 2013). "Thus, the different importance of certain cell populations serving as IL-10 source might depend on the specific tissue, the cell population affected and the time after infection." (PMID 24244162, 2013). "Indeed, DCs are the major sources of IL-10, secreting this cytokine particularly in the late phase of their immune response (∼24 hours after infection), in contrast to the pro-inflammatory cytokines whose secretion they start from a relatively early period (few hours after infection)." (PMID 23667643, 2013). "However, the frequency of dogs producing high levels of IL-10 increased after 270 days of infection, suggesting that the production of this cytokine might contribute to infection severity." (PMID 23577121, 2013). "A particular type of regulatory cell that could be involved in an infection-triggered immune regulatory chain of events is the IL-10-secreting Th1 cell, since, contrasting with other regulatory cells, it is not anergic, and would, therefore, be more easily driven to expansion." (PMID 24115950, 2013). "Given that the most pronounced small intestinal immunopathology correlated with increased levels of Th2 cytokines and IL-10 produced in mLN, we were further interested whether the acute phase of infection was accompanied by distinct shifts within the composition of the intestinal microbiota." (PMID 24040152, 2013). "Additionally, at 14-weeks postinfection IL-10 KO mice had totally cleared the infection." (PMID 24069337, 2013).